CHD4 (chromodomain helicase DNA binding protein 4)
Diseases named in the same sentence as CHD4 in open-access papers (continued):
Sharing a sentence is not in itself a finding about the gene and the disease.
tumor (continued). "CHD4 is a participant in histone deacetylation, and studies have shown that the abnormal expression of CHD4 is related to the occurrence and development of tumours." (PMID 36681835, 2023). "Further, CHD4 silencing or knockdown provoked expected outcomes i.e. suppression of tumor proliferation and migration via cell cycle cessation at the G1/S phase." (PMID 37483794, 2023). "CHD4 is an essential, widely conserved ATP-dependent translocase that is also a broad tumour dependency." (PMID 36473839, 2022). "CHD4 acts as a tumor suppressor gene in female cancers (i.e., ovarian cancer), promoting DNA repair similar to the BRCA gene, reducing proliferation, and increasing sensitivity to DNA damaging agents." (PMID 34142021, 2021). "As a component of the NuRD complex, CHD4 controls chromatin accessibility and mediates the downregulation of many genes whose products contribute to the DNA damage response, tumor malignancy, and cell cycle control." (PMID 33981601, 2021). "In animal model, we found that tumor growth in CHD4-depleted cells was lower than that in parental cells, suggesting that high expression of CHD4 promoted tumor growth in CRC." (PMID 33994851, 2021). "In animal models, the depletion of CHD4 affected CRC tumor growth, and the combination of a histone deacetylase 1 (HDAC1) inhibitor and platinum drugs inhibited CHD4 expression and increased the cytotoxicity of platinum drugs." (PMID 33994851, 2021). "The IHC staining revealed high CHD4 expression in shLAcZ and low CHD4 expression in shCHD4 tumor tissues." (PMID 33994851, 2021). "It has been showed that CHD4 maintains the epigenetic silencing of tumor suppressor genes including E-cadherin." (PMID 33419089, 2021). "CHD4 has been shown to maintain the epigenetic suppression of multiple tumor suppressor genes including E-cadherin." (PMID 33419089, 2021). "Higher CHD4 expression is positively correlated with metastatic stage, tumor recurrence, and survival status.High CHD4 expression at the level of mRNA and protein significantly correlated with shorter survival." (PMID 33981601, 2021). "Our results indicated that most CRC patients had higher CHD4 expression in tumor tissues than in normal tissues." (PMID 33994851, 2021). "Recent studies have indicated that CHD4 has oncogenic functions that inhibit multiple tumor suppressor genes through epigenetic regulation." (PMID 33994851, 2021). "Mechanistically, NuRD complex containing CHD4 localizes to super-enhancers where CHD4 generates a chromatin architecture permissive for the binding of the tumor driver and fusion protein PAX3-FOXO1, allowing downstream transcription of its oncogenic program." (PMID 32744500, 2020). "(A and B) Violin and boxplots depicting CHD4 expression levels (data: r2.aml.nl) in normal (grey) and tumor tissue (orange)." (PMID 32744500, 2020). "The results showed that the expression level of CHD4 was significantly associated with TNM stage(P = 0.001), tumor size(P = 0.002) and lymph node metastasis (P = 0.005)." (PMID 32228507, 2020). "Nonetheless, the role of CHD4 in DNA-damage repair and genome integrity should be further explored in the context of general tumor sensitivity." (PMID 32744500, 2020). "More recently, CHD4 expression was found to be positively correlated with metastatic stage, tumor recurrence and survival status in triple-negative breast cancer (TNBC)." (PMID 32577620, 2019). "We previously found CHD4 is required to maintain GBM tumour initiating cell morphology and stem cell marker expression." (PMID 30872624, 2019). "In contrast, exposing CHD4-suppressed GBM tumour initiating cells did result in an increase in γH2Ax expression, which was not resolved to endogenous levels after 24 hours." (PMID 30872624, 2019).
tumor (continued). "In CRCs, CHD4 knockdown activates TSGs and blunts proliferation, invasion, and metastases of tumor cells." (PMID 31438571, 2019). "The role of CHD4 was elucidated by analyzing the relationships between clinical and pathological features, including tumor response after CCRT." (PMID 31438571, 2019). "CHD4 mRNA is significantly upregulated in GBM patients (n = 528) compared with non-tumour controls (n = 10) in the TCGA dataset (p = 2.2e-05)." (PMID 30872624, 2019). "An oncogenic role was ascribed to CHD4 for initiating and supporting tumor-suppressor gene silencing in human colorectal cancer." (PMID 30563971, 2018). "In 7978 sequenced TCGA tumor samples, four CHD genes—CHD4, CHD5, CHD6, and CHD7—exhibited mutations in more than 200 tumor samples." (PMID 28649742, 2017). "In contrast to CHD3 and CHD5, which most likely function as tumor suppressors, the role of CHD4 in various tumors appears to be quite complex." (PMID 28055972, 2017). "Since the human in vivo shRNA screen has been performed in immunodeficient animals, we investigated the role of CHD4 in a model in which tumor develops in the presence of an intact immune system." (PMID 27779108, 2016). "CHD4 silencing significantly reduced tumor growth in vivo and proliferation in vitro of MCF10DCIS.com cells." (PMID 27779108, 2016). "CHD4 expression was reported to be reduced in gastric and colorectal cancers with microsatellite instability, as is often seen for classic tumour-suppressor genes." (PMID 23697937, 2013). "In malignancy, CHD4 has context-dependent functions as a tumor suppressor and an oncogene." (PMID 40501592, 2025). "Hence, PARP inhibitor AG-014699 and the suberohydroxamic acid as an HDAC inhibitor have been shown to inhibit CHD4 function and tumor growth in a mouse xenograft model of EpCAM+ hepatocellular carcinoma." (PMID 41278204, 2025). "CHD4 has been shown to regulate tumor growth in MDA-MB-231 cells." (PMID 38281186, 2024). "Interestingly, almost all tumour-associated proteins, including the oncogenes DEK and CHD4 and the tumour-suppressor gene MYH9, were expressed at lower levels in LM4 than in T4." (PMID 36691026, 2023). "In recent years, studies have shown that the abnormal expression of CHD4 is related to the development of tumours, but it was previously unclear whether it acts as a tumour suppressor gene or an oncogene." (PMID 36681835, 2023). "Low CHD4 mRNA expression was significantly associated with FIGO stage (stage I vs. stage III; p = 0.0018; stage I vs. stage IV; p = 0.0010; stage II vs. stage III; p = 0.0411; stage II vs. stage IV; p = 0.0321) and tumour grade (G; p = 0.0331)." (PMID 36681835, 2023). "Furthermore, in fusion-positive rhabdomyosarcoma, CHD4/NuRD colocalized with P3F at a SE, allowing tumor cell maintenance and survival." (PMID 37501079, 2023). "We showed the role of CHD4 in tumor progression, metastasis and stemness in PTC cells." (PMID 33419089, 2021). "In addition, the result of Clinical Proteomic Tumor Analysis Consortium (CPTAC) analysis also showed that CHD4 protein expression in CRC tissues was also higher than it in normal tissues." (PMID 33994851, 2021). "Therefore, if CHD4 inhibitors are therapeutically tested, a targeted drug delivery system must be developed to direct this drug into the tumor to decrease the chances of affecting healthy cells or other unwanted secondary effects." (PMID 34142021, 2021). "In summary, we found that CHD4 was overexpressed in tumor tissues in CRC patients." (PMID 33994851, 2021). "In vitro experiments have recently suggested that CHD4 depletion may be a therapeutic target in different types of BC, as it could lead to reduced tumor proliferation, migration, invasiveness, and growth." (PMID 33981601, 2021).
tumor (continued). "In this study, we evaluated the role of CHD4 in regulating several malignant characteristics, such as cell proliferation, motility, drug sensitivity, and tumor growth, through clinical databases, clinical samples, in vitro cell models, and in vivo animal models." (PMID 33994851, 2021). "CHD4 expression was higher in the nuclei of tumor cells than in normal colon epithelial cells." (PMID 33994851, 2021). "Tumor volume was much decreased (P = 0.025) in the CHD4-down-regulated A549 cells, suggesting that CHD4 suppression could significantly decrease tumorigenicity in nude mice." (PMID 32228507, 2020). "However, in a recent study, CHD4 was found to be one of the tumor suppressing TF (transcriptional factor) in lung cancer." (PMID 32228507, 2020). "Our results suggest that in addition to its direct regulatory roles in HCC cells, the CHD4/NuRD complex may also have an impact on tumor immune microenvironment of HCC." (PMID 32070428, 2020). "All tumor types represented in both datasets were sensitive to CHD4 depletion." (PMID 32744500, 2020). "We believe that this broad tumor dependency on CHD4 might be partially explained by its positive contribution to the activity of oncogenic transcription factors at super-enhancers." (PMID 32744500, 2020). "Besides this pediatric malignancy, CHD4 is essential for the survival of a broad range of tumor types." (PMID 32744500, 2020). "(C) Databases used to evaluate tumor sensitivities to CHD4 silencing or knockout." (PMID 32744500, 2020). "Noteworthy, after neoadjuvant CCRT, CHD4 expression was significantly correlated with advanced tumor and nodal status, post-CCRT and low tumor regression, which indicated that CHD4 is involved in therapeutic responses, which corresponded with clinical treatments." (PMID 31438571, 2019). "Recent studies suggest the roles CHD4 in both promoting and suppressing tumor growth." (PMID 32577620, 2019). "As ERBB2+ BC cells heavily depend on ERBB2 receptor signaling for their growth and survival, and because CHD4 depletion inhibits BC tumor development in the MMTV/NeuT model, we hypothesized that CHD4 silencing might impair the ERBB2 signaling pathway." (PMID 30967373, 2019). "However, due to the crucial roles of CHD4 in both promoting and suppressing tumor growth, more knowledge of the fundamental biology downstream of CHD4 should be investigated." (PMID 32577620, 2019). "Chd4 silencing significantly reduced (about 67%) tumor growth in vivo." (PMID 27779108, 2016). "Although CHD4 has a somewhat complicated relationship with the cell cycle, recent evidence indicates that CHD4 may exert some tumour-suppressor functions in human carcinogenesis." (PMID 23697937, 2013). "Despite this complex relationship with the cell cycle, recent evidence has indicated that CHD4 may play a tumour-suppressor function in some tumour types." (PMID 23697937, 2013). "However, in its role as a DNA-repair protein, CHD4 functions as a tumour suppressor alongside proteins such as BRCA1." (PMID 23697937, 2013). "Together, these findings show that FBXW7 physically interacts with CHD4 and mediates its ubiquitination, which highlights that targeting CHD4 may be a promising therapeutic strategy for eradicating BCSCs to overcome tumor relapse, metastasis and drug resistance in TNBC." (PMID 38268032, 2024). "In the absence of CHD4, the SE lost its accessibility to DNA, causing tumor cell death." (PMID 37501079, 2023). "In addition, CHD4 regulated tumor growth rate and drug sensitivity." (PMID 33994851, 2021). "Importantly, high CHD4 expression was strongly associated with aggressive tumor behavior and poor overall survival of NSCLC patients, indicating that CHD4 could be used as an independent factor for predicting NSCLC patient prognosis." (PMID 32228507, 2020).
tumor (continued). "Therefore, we wondered whether the CHD4/NuRD complex had an impact on tumor immune microenvironment in HCC." (PMID 32070428, 2020). "Therefore, we questioned if CHD4 constitutes a general tumor dependency." (PMID 32744500, 2020). "Hence, further studies investigating the role of CHD4 in repression of gene expression in the context of FP-RMS are necessary to fully understand the function of this remodeler in the expression signature of this tumor." (PMID 32744500, 2020). "For example, OGG1 recruits chromodomain helicase DNA binding protein 4 (CHD4) and enhancer of zeste homolog 2 (EZH2) to sites of 8-oxoG formation in promoters of tumor suppressor genes." (PMID 41465236, 2025). "In order to investigate the role of CHD4 in patients with HNSCC, we systematically analyzed tumor tissue of HNSCC patients included in the Cancer Genome Atlas (TCGA) HNSCC cohort concerning CHD4 gene expression levels and HPV status." (PMID 38594331, 2024). "Accumulating evidence has revealed that CHD4 is highly expressed in TNBC tissues and significantly positively correlated with tumor metastasis status, tumor recurrence, and poor prognosis." (PMID 38268032, 2024). "Progressive tumor prognosis indicated by enhanced growth, migration, and proliferation of NSCLC cells was correlated to the over-expression of CHD4 along with deprived survival of patients." (PMID 37483794, 2023). "The tumour specificity of the gene knockout was tested in neural foetal stem cells (NSC), and our results show that the genes UBE2N, CHD4, LSM11, EED, KANSL1 and KANSL3 are essential for CSC growth and suggest them as therapeutic candidates in paediatric HGG." (PMID 37161535, 2023). "The expression of the CHD4/NuRD complex inversely correlates with CD8 T cell and DC cell infiltration in HCC, both are critical for tumor immune surveillance." (PMID 32070428, 2020). "To investigate the function of the NuRD complex on the genome level, we performed ChIP-seq assays in RH4 cells for CHD4, RBBP4, HDAC2, and MTA2, as well as for the tumor driver P3F, and other relevant epigenetic regulators and histone marks." (PMID 32744500, 2020). "Given that CHD4 is overexpressed in NSCLC and functions as a novel tumor-promoting gene in NSCLC, we further sought to determine the mechanisms underlying CHD4-mediated promotion of NSCLC cell migration and proliferation." (PMID 32228507, 2020). "We compared CHD4 protein expression in multiple GBM cell lines (LN229, U251 and U87), tumour initiating cells (TS667, TS665 and BT112), and normal human astrocytes (NHA)." (PMID 30872624, 2019). "When we depleted CHD4, there was decreased RAD51 protein and mRNA in GBM cell lines and tumour initiating cells." (PMID 30872624, 2019). "We confirmed the predictive and prognostic significance of CHD4 expression in CCRT treatment, and its correlation with other clinicopathological features, such as tumor regression grade (TRG), therapeutic response, and patient survival." (PMID 31438571, 2019). "The genes CHD4 and SMARCA4 demonstrate how the landscape of tumor type – driver gene connections can be exploited to identify novel therapeutic targets, especially for patients without a canonical driver mutation." (PMID 29030609, 2017). "To investigate the effect of CHD4 in a preclinical context, we developed a human metastatic breast cancer (MBC) model by direct implantation of patient-derived tumor tissue into the mammary fat pad of NSG mice to obtain a xenograft model (PDX)." (PMID 27779108, 2016). "Depletion of CHD4 significantly decreases cell proliferation and migration in HER2-positive and triple-negative breast cancer cell lines, leading to a reduction in tumor mass in luminal B and HER2-ortholog-activated triple-negative PDX and transgenic mouse models." (PMID 41278204, 2025).
tumor (continued). "In addition, integrative analyses of genome-wide cancer dependency datasets have identified CHD4 as a broader oncogenic vulnerability, suggesting that its role in maintaining chromatin architecture and transcriptional output may be essential across multiple tumor types." (PMID 40508013, 2025). "Bioinformatics analysis using the TargetScan database indicated that the oncomiR, hsa-miR-194-5p, is the most likely miR that functions as an upstream regulator of CHD4, a member of the human chromodomain helicase DNA-binding (CHD) protein family that plays a critical role in tumor development." (PMID 40746882, 2025). "Importantly, hsa-miR-5p has been suggested to regulate CHD4 via the PI3K/AKT signaling pathway, thereby contributing to the poor prognosis of OSCC by enhancing tumor resistance to programmed cell death by anoikis." (PMID 40746882, 2025). "A NuRD-targeted CRISPR-Cas9 screen revealed that FP-RMS cells are uniquely sensitive to CHD4 depletion compared to other NuRD components, indicating a non-redundant, lineage-specific role for CHD4 in this tumor type." (PMID 40508013, 2025). "CHD4 insufficiency reduced immune suppression, as could be observed by elevated CD4+ and CD8+ T cell populations within the tumor, and enhanced the effectiveness of antitumor T-cell responses in melanoma-bearing mice treated with an anti-PD-1 antibody." (PMID 39519018, 2024). "We found that even in the absence of external DNA damage, CHD4 suppression caused an increase in phosphorylated H2Ax (γH2Ax) in GBM cell lines and tumour initiating cells, indicating an increase in DNA DSBs." (PMID 30872624, 2019). "Similarly, CHD4 mRNA expression is significantly upregulated in GBM (n = 219, p = 2.3e-14) compared with non-tumour patient samples (n = 28) in the Rembrandt dataset." (PMID 30872624, 2019). "Similarly, the upregulation of CHD4 has been reported in CRC patients with poor tumor differentiation, higher tumor nodal metastases status, stage, shorter overall survival, and higher recurrence." (PMID 31438571, 2019). "Moreover, in vitro CHD4 depletion in TNBC (one of the most aggressive BC subtypes) was reported to significantly reduce cell proliferation and migration, and dramatically reduce tumor mass in vivo." (PMID 33981601, 2021). "However, there are no reports on the correlation between CHD4 upregulation and other pathological features, such as vascular invasion, perineural invasion, and most importantly, treatment response (tumor regression grade)." (PMID 31438571, 2019). "Thus, hypoxia rather than CHD4 seems to be a major regulator of their expression in human tumours." (PMID 33741961, 2021). "However the roles of VEGF-A, CHD4 and TCF20 genes in CK20-related micrometastasis are unknown, the expression of them in LNs from Tumor-Node-Metastasis (TNM) stage III and IV CRC patients would be studied in order to know whether this micrometastasis pathway is preserved in metastatic LNs." (PMID 29467924, 2018). "Despite this strong co-regulation, no negative correlation with CHD4. was seen suggesting there may be alternative mechanisms regulating PADI1 and PADI3 co-expression in tumours." (PMID 33741961, 2021).
neurodevelopmental disorder (6 papers, 2023 to 2025). A behavioral and cognitive disorder with onset during the developmental period that involves impaired or aberrant development of intellectual, motor, or social functions. "In contrast, genes downregulated in SMS cortical neurons are involved in anatomical structure and multicellular organism development, including genes implicated in neurodevelopmental disorders (i.e., CHD4, UBE3B, KDM5B, and SETD1B)." (PMID 40882620, 2025). "Finally, CHD5 mutations have recently been identified as causing a neurodevelopmental disorder that is clinically very similar to those associated with CHD3 and CHD4 mutations." (PMID 40004235, 2025). "Another interacting partner CHD4 is involved in a multisystemic neurodevelopmental disorder." (PMID 38025430, 2023). "CHD4 is also related to cardiac development and neurodevelopmental disorders." (PMID 36826468, 2023).